BACE2 (beta-secretase 2)
Description:
Responsible for the proteolytic processing of the amyloid precursor protein (APP). Cleaves APP, between residues 690 and 691, leading to the generation and extracellular release of beta-cleaved soluble APP, and a corresponding cell-associated C-terminal fragment which is later released by gamma-secretase. It has also been shown that it can cleave APP between residues 671 and 672. Involved in the proteolytic shedding of PMEL at early stages of melanosome biogenesis. Cleaves PMEL within the M-beta fragment to release the amyloidogenic PMEL luminal fragment containing M-alpha and a small portion of M-beta N-terminus. This is a prerequisite step for subsequent processing and assembly of PMEL fibrils into amyloid sheets. Responsible also for the proteolytic processing of CLTRN in pancreatic beta cells.
Synonyms: ASP1; DRAP; AEPLC; ALP56; ASP21; CDA13; CEAP1; BAE2
Tractability: Small molecule: a structure with a bound ligand is known; a high-quality ligand is known; it has a high-quality binding pocket; it belongs to a druggable protein family. Antibody: UniProt places it where antibodies can reach, with high confidence; its Gene Ontology location is reachable by antibodies, with high confidence; UniProt predicts a signal peptide or a membrane-spanning region. PROTAC: ubiquitination databases record sites on it; a small molecule that binds it is known.
Target class: Aspartic protease; Aspartic protease A1A subfamily; Protease; Enzyme; Aspartic protease AA clan
Chemical probes: AM-6494 (high quality), Lanabecestat (high quality), VERUBECESTAT, atabecestat (high quality)
Gene: Protein-coding gene on chromosome 21 (41,167,801 to 41,282,530, forward strand). Ensembl gene ENSG00000182240.
Subcellular location: Cell membrane; Golgi apparatus; Endoplasmic reticulum; Endosome; Melanosome
Gene Ontology:
Molecular function: aspartic-type endopeptidase activity; protein binding
Biological process: glucose homeostasis; melanosome organization; membrane protein ectodomain proteolysis; negative regulation of amyloid precursor protein biosynthetic process; protein processing; amyloid-beta metabolic process; peptide hormone processing; proteolysis
Cellular component: Golgi apparatus; melanosome; melanosome membrane; plasma membrane; endosome; membrane; trans-Golgi network; endoplasmic reticulum
Genetic constraint (gnomAD): Loss-of-function variants: 15 observed, 40.24 expected, observed/expected ratio (o/e) 0.37, 90% interval 0.25 to 0.57. The upper end of that interval is the gene's LOEUF score, 0.57, which puts it in group 2 of 6, group 1 being the genes least tolerant of losing a copy. Missense variants: 594 observed, 645.17 expected, observed/expected ratio (o/e) 0.92, 90% interval 0.86 to 0.99. Synonymous variants: 277 observed, 271.83 expected, observed/expected ratio (o/e) 1.02, 90% interval 0.92 to 1.13.
Homologues: Orthologues: chimpanzee BACE2 (99% identical), dog BACE2 (90% identical), mouse Bace2 (89% identical), rat Bace2 (89% identical), macaque BACE2 (86% identical), guinea pig BACE2 (82% identical), tropical clawed frog bace2 (63% identical), rabbit BACE2 (55% identical), zebrafish bace2 (40% identical), Drosophila melanogaster CG17134 (21% identical), Drosophila melanogaster CG6508 (19% identical), Drosophila melanogaster Bace (19% identical), and 11 more. Paralogues in human: BACE1 (45% identical), PGC (23% identical), PGA3 (22% identical), PGA4 (22% identical), PGA5 (22% identical), NAPSA (21% identical), CTSD (21% identical), CTSE (20% identical), REN (20% identical).
Diseases named in the same sentence as BACE2 in open-access papers:
BACE2 is named in the same sentence as 68 diseases in open-access papers, as found by Europe PMC text mining. Sharing a sentence is not in itself a finding about the gene and the disease. The quoted sentences say what the papers report.
Alzheimer disease (42 papers, 2009 to 2025). A progressive, neurodegenerative disease characterized by loss of function and death of nerve cells in several areas of the brain leading to loss of cognitive function such as memory and language. "The Alzheimer’s disease–linked protease BACE2 modulates lymphangiogenic VEGFR3 signaling, and BACE2-cleaved soluble VEGFR3 has utility as a pharmacodynamic plasma marker for BACE2 activity in vivo." (PMID 38888964, 2024). "Though BACE2 is also expressed in the brain, some reports revealed the protective effect of the enzyme towards Alzheimer's disease, by reducing the pathogenic forms of Aβ being produced within the cells that expressed both BACE1 and BACE2." (PMID 25254246, 2014). "While Bace1 is mainly associated with amyloid-β (Aβ) production in Alzheimer’s disease, its structural homology to Bace2 suggests that its inhibition may also impact melanin synthesis." (PMID 40286213, 2025). "The BACE2 gene is linked to increased risk and earlier disease onset of Alzheimer’s disease." (PMID 37893151, 2023). "Another noteworthy DMR was associated with APP-cleaving enzyme 2 coding gene (BACE2) encoded protein that cleaves amyloid precursor protein into amyloid beta peptide, and is implicated in the pathogenesis of neurodegenerative diseases including Alzheimer’s disease." (PMID 30545422, 2018). "BACE2 was firstly studied for its role in the formation of the amyloid peptides involved in the pathogenesis of Alzheimer disease." (PMID 38199984, 2024). "Overall, we also found other important DEGs, viz., BACE1 and BACE2, which belong to a class of proteases called β-secretases that are extensively studied in Alzheimer’s disease." (PMID 37218885, 2023). "The nominal “Alzheimer’s disease” pathway is the foremost one identified by BioPlanet for the discriminant gene set for FDG-18, implicated via the influence of BACE2 and NDUFS4." (PMID 35774552, 2022). "We also identified that BACE2, participating in the Alzheimer’s disease pathway, was one of the top DEGs in both the IBD and tumor enteroids in the current study." (PMID 35884586, 2022). "BACE2, which is involved in Alzheimer’s disease, was found to be one of the most prevalent DEGs in the IBD enteroids compared to the tumor enteroids." (PMID 35884586, 2022). "This study advances our understanding of the regulation of BACE2 and provides a potential mechanism of its dysregulation in Alzheimer’s disease." (PMID 32160867, 2020). "Among those genes, Apaf1, Bace2, and Plcb4 were enriched in the “Alzheimer's disease-reference pathway” and downregulated after ME intervention." (PMID 25580148, 2014). "BACE2 is a molecule that has been well studied in neurodegenerative diseases as the enzyme cleaving APP, the precursor of amyloid-β peptides (Aβ), a hallmark of Alzheimer’s disease." (PMID 33413577, 2021). "Prior studies have noted the importance of BACE2 in Alzheimer's disease (AD) and type 2 diabetes." (PMID 31856384, 2020). "It indicates that BACE2 dysregulation might be mediated by the proteasomal and lysosomal impairment in Alzheimer’s disease." (PMID 32160867, 2020). "β-Site APP-cleaving enzyme 1 (BACE1) inhibition to treat Alzheimer’s disease also inhibits BACE2." (PMID 30456346, 2018). "BACE2, a member of beta-site APP-cleaving enzyme family of genes, encodes an integral membrane glycoprotein that functions as an aspartic protease related to Alzheimer's disease." (PMID 27738332, 2016). "Beta-site APP-cleaving enzyme 2, BACE2, is an aspartyl protease commonly associated with BACE1, a related homolog responsible for amyloid processing in the brain and strongly implicated in Alzheimer’s disease." (PMID 26840340, 2016). "Since BACE1 activity is known to cause Alzheimer's disease, it is essential to design a selective drug that could specifically target BACE1 over BACE2." (PMID 25254246, 2014).
Alzheimer disease (continued). "Further, it would be interesting to define which are the mechanisms that drive the over-expression of BACE2 in different cancer subtypes looking at SNP (single nucleotide polymorphism) and CNV (copy number variation) as it was reported for patients affected by Alzheimer’s disease." (PMID 33926496, 2021). "Trisomy 21 (T21) confers increased gene dosage of the amyloid precursor protein (APP) and other proteins (BACE2, S100β, DYRK1A, RCAN1) involved in Alzheimer's disease (AD) pathology." (PMID 40536124, 2025). "BACE2, along with BACE1, has been extensively studied in the context of Alzheimer’s disease, as both enzymes are responsible for processing APP into neurotoxic Aβ peptides." (PMID 39109301, 2024). "β-site APP-cleaving enzyme 2 (BACE2) is a homolog of BACE1, which is considered as the most promising therapeutic target for Alzheimer’s disease (AD)." (PMID 35110536, 2022). "β-Site APP-cleaving enzyme 1 (BACE1) inhibition is considered one of the most promising therapeutic strategies for Alzheimer’s disease, but current BACE1 inhibitors also block BACE2." (PMID 30456346, 2018). "Despite BACE1 and BACE2 were discovered simultaneously, BACE1 captured first the attention of the scientific community mainly for its role in regulating the formation of cytotoxic Aβ peptides in Alzheimer's Disease (AD)." (PMID 33926496, 2021). "β-site APP-cleaving enzyme 2 (BACE2), the homolog of BACE1, might play a complex role in the pathogenesis of Alzheimer’s disease as it is not only a θ-secretase but also a conditional β-secretase." (PMID 32160867, 2020). "BACE1 competes with BACE2 over APP substrate, but their enzymatic activity generates different type of products in which the product of BACE1 but not BACE2 leads to Alzheimer's disease." (PMID 25254246, 2014). "While these documents are directed towards the discovery of therapeutic candidates for Alzheimer's disease, they often include inhibition data against the paralogue BACE2 even thought this is not currently considered a drug target." (PMID 20298516, 2009). "Thus, this study identifies BACE2 as a modulator of lymphangiogenic VEGFR3 signaling and demonstrates the utility of sVEGFR3 as a pharmacodynamic plasma marker for BACE2 activity in vivo, a prerequisite for developing BACE1-selective inhibitors for safer prevention of Alzheimer’s disease." (PMID 38888964, 2024).
dementia (9 papers, 2014 to 2023). Loss of intellectual abilities interfering with an individual's social and occupational functions. "We looked into our cohort of 67 DS cases with dementia for the effect of BACE2 variants in age of onset of dementia." (PMID 24462566, 2014). "In summary, we find variants in BACE2 that possibly affect the AOO of dementia in DS, suggesting a potential role of BACE2 in AD and DS." (PMID 24462566, 2014). "Interestingly, SNPs in BACE2 gene are associated with the onset age of dementia among DS patients, and a de novo intronic deletion within a single BACE2 allele has been reported to cause EOAD in a 50-year-old euploid patient." (PMID 33530458, 2021). "BACE2 variants have an effect on the age of onset of dementia in people with Down syndrome." (PMID 25563673, 2014). "BACE2 encodes a glycoprotein that splits APP into AβP, which promotes the amyloid plaque formation in AD and the brain with DS causing dementia." (PMID 35676933, 2022). "Combined, our data prove the physiological role of BACE2 as a dose-sensitive AD-suppressor gene, potentially explaining the dementia delay in ~30% of people with DS." (PMID 32647257, 2021). "This suggests that one or several duplicated genes in DS may provide partial protection against the pro-hemorrhagic effects of APP duplication similarly to BACE2 involvement in age at onset of dementia in DS." (PMID 37170141, 2023). "We attempted to look into the role of BACE2 in AOO of dementia in DS." (PMID 24462566, 2014). "The upregulation of the APP-related system in DS may explain why BACE2 SNPs are not found to be associated in general AD genome-wide association study, but are suggestive when the dementia cohort is made up of APP trisomy, as in the present study." (PMID 24462566, 2014). "Not only the APP gene is responsible for dementia in DS, GATD3A, SOD1, ERG, BACE2, DSCR1/RCAN1, APOE (19q13.32), BACE1 (11q23.3), IL1B (2q14.1), GSAP (7q11.23), UBB (17p11.2), and IRS1 (2q36.3) genes may also play a major role in dementia in DS." (PMID 35676933, 2022).
glioma (8 papers, 2020 to 2024). A benign or malignant brain and spinal cord tumor that arises from glial cells (astrocytes, oligodendrocytes, ependymal cells). "We demonstrated for the first time that higher levels of BACE2 expression are associated with a higher grade of human glioma, the mesenchymal molecular subtype of GBM and a worse prognosis." (PMID 31856384, 2020). "High BACE2 expression was related to wild‐type IDH1 in glioma patients, while low BACE2 expression was associated with other features, including MGMT promoter methylation, 1p/19q codeletion, TERT loss and ATRX mutation." (PMID 31856384, 2020). "However, few reports on BACE2 expression patterns, the clinical significance of BACE2 in human gliomas and the underlying mechanisms of BACE2 function were found in the literature." (PMID 31856384, 2020). "Here, we report that increased beta‐site APP‐cleaving enzyme 2 (BACE2) expression is associated with increases in the grade of human glioma, the incidence of the mesenchymal molecular glioblastoma multiforme subtype and the likelihood of poor prognoses for patients." (PMID 31856384, 2020). "Thus, the expression level of BACE2 is associated with a higher grade of human glioma." (PMID 31856384, 2020). "In contrast, the overexpression of β-secretase can promote the rapid proliferation of glioma cells, while the decreased activity of β-secretase (BACE2) can effectively inhibit the growth of glioma." (PMID 39634655, 2024). "In line with our observations, KPNA2, DTL, BACE2 and DTYMK were previously found to be associated with tumour stage also in other cancers, including hepatocellular carcinoma or glioma." (PMID 36320118, 2022). "Based on the TCGA database, GBM samples expressed higher BACE2 expression than normal tissues or low-grade gliomas, and BACE2 mRNA levels were significantly higher in the MES subtype." (PMID 33413577, 2021). "In glioma, BACE2 has been shown to increase migration and invasion by inducing an epithelial to mesenchymal transition." (PMID 33926496, 2021). "Further, BACE2 silencing in glioma was shown to decrease tumor volume in mice and to increase the effect of radiation therapy." (PMID 33926496, 2021). "Correlation of BACE2 expression in human glioma patients with different clinicopathological features." (PMID 31856384, 2020). "Altogether, these findings suggested that BACE2 is a crucial molecule that promotes cell invasion, migration and the mesenchymal transition in human gliomas." (PMID 31856384, 2020). "By immunofluorescence, we found that knocking down BACE2 led to F‐actin cytoskeletal changes in gliomas." (PMID 31856384, 2020). "This observational study suggests that BACE2 can be used as a potential gene target for therapy in glioma patients." (PMID 31856384, 2020). "In summary, these results indicated that BACE2 advanced the malignancy of glioma through these malignant processes." (PMID 31856384, 2020). "In the present study, we used publicly datasets to investigate the relationship between BACE2 expression levels and tumour grade or the clinicopathological and molecular features of gliomas." (PMID 31856384, 2020). "The levels of p‐p65 and p65 were determined in transfected glioma cells, and knocking down BACE2 led to p‐p65 downregulation." (PMID 31856384, 2020). "Silencing of BACE2 in glioma cells led to cell cycle arrest at G0‐G1 and suppressed tumour growth in xenograft mice, while BACE2 overexpression decreased the proportion of cells in the G0‐G1 phase of the cell cycle." (PMID 31856384, 2020). "Next, the expression of BACE2 was upregulated with increasing concentrations of TGFβ1 in the medium for both glioma cell lines." (PMID 31856384, 2020). "Correlation univariate Cox regression and multivariate Cox regression of BACE2 expression for overall survival of glioma patients." (PMID 31856384, 2020). "The signalling pathway that regulates BACE2 expression in gliomas is vital in exploring therapeutic treatments." (PMID 31856384, 2020).
glioma (continued). "A correlation analysis of the whole‐genome profile of BACE2 was performed with the TCGA database to explore potential biological effects of gliomas." (PMID 31856384, 2020). "Being chaperoned by csGRP78 for lysosomal degradation, BACE2 silencing suppressed in vitro and in vivo tumorigenesis capability of glioma stem cells, demonstrating that csGRP78 engages in the regulation of cancer stemness in glioma." (PMID 35883497, 2022). "The GSEA database indicated that BACE2 could be involved in cell invasion and cell migration in gliomas." (PMID 33653351, 2021). "Very recently, we and other groups showed an upregulation of BACE2 also in melanoma and in glioma." (PMID 33926496, 2021). "Importantly, high BACE2 expression correlates with worse prognosis in melanoma pancreatic cancer and glioma, implicating an active role of this protease in cancer progression." (PMID 33926496, 2021). "For instance, the pro-tumoral effect of BACE2 has been observed in glioma and ocular melanoma." (PMID 33926496, 2021). "More recently, BACE2 have been reported to be highly expressed also in other types of tumors, such as glioma and melanoma, where different mechanisms have been revealed to explain how processing of amyloidogenic proteins can drive tumor growth and promote drug resistance." (PMID 33926496, 2021). "Taken together, our findings indicate that BACE2 might be a novel prognostic biomarker and a potential therapeutic target for human gliomas." (PMID 31856384, 2020). "Our study indicated that BACE2 plays a significant role in glioma development." (PMID 31856384, 2020). "The biological processes assessed and the GSEA indicated that BACE2 may, indeed, be involved in cell invasion, cell migration and the mesenchymal transition in gliomas." (PMID 31856384, 2020). "Additionally, as observed using immunofluorescence, knocking down BACE2 decreased the formation of invadopodia, an important structure in the invasive growth of cancer, in gliomas." (PMID 31856384, 2020). "First, BACE2 silencing led to glioma cell morphological transformation." (PMID 31856384, 2020). "In addition, we investigated the potential biological process through which BACE2 promotes glioma malignant development and evaluated the expression levels of some key regulators of the cell cycle, including CDK2, CDK4, cyclin D1, p21 and p27." (PMID 31856384, 2020). "Furthermore, the BACE2 expression level was also related to the clinicopathological characteristics of glioma patients in the TCGA database." (PMID 31856384, 2020). "Furthermore, BACE2 knockdown suppressed the phosphorylation of IKKβ induced by TNF‐α in glioma cells." (PMID 31856384, 2020). "In summary, these results strongly suggested that BACE2 might serve as a prognostic biomarker in glioma." (PMID 31856384, 2020). "BACE2 may serve as a novel biomarker and a potential therapeutic target in the treatment of human glioma." (PMID 31856384, 2020). "Furthermore, mesenchymal markers, including N‐cadherin, β‐catenin and Vimentin; the epithelial marker E‐cadherin; and upstream transcription factors, including Snail and Twist, were regulated by BACE2 in gliomas." (PMID 31856384, 2020). "In addition, the levels of BACE2 mRNA and protein in the human glioma samples and normal brain tissues from Qilu Hospital (Jinan, China) were analysed by RT‐qPCR and IHC." (PMID 31856384, 2020). "However, further research should be undertaken to investigate the potential molecular mechanisms that coordinate BACE2 and TGFβ1 signalling in gliomas." (PMID 31856384, 2020). "Therefore, BACE2 is a potential therapeutic target for human gliomas due to its function and ability to be regulated." (PMID 31856384, 2020). "In addition, the expression of BACE2 was significantly upregulated in the mesenchymal molecular subtype of human glioma." (PMID 31856384, 2020).